SDC1 (syndecan 1)
Diseases named in the same sentence as SDC1 in open-access papers (continued):
Sharing a sentence is not in itself a finding about the gene and the disease.
adenoma (3 papers, 2008 to 2021). A neoplasm arising from the epithelium. "Syndecan-1 expression was examined by immunohistochemistry of a tissue microarray containing cores from 158 colorectal adenocarcinomas and 15 adenomas linked to a Cleveland Clinic, IRB-approved database with a mean clinical follow-up of 38 months." (PMID 18590537, 2008). "Loss of syndecan-1 immunoexpression was observed in 72 (42.6%), 5 (12.2%), and 3 (8.1%) cases of CRC, adenomas, and normal mucosae, respectively." (PMID 33437261, 2021). "It has been reported that syndecan-1 expression is decreased in colorectal adenocarcinomas in comparison to adenomas and the normal tissue, and that reduced expression correlates with the incidence of local metastases." (PMID 18590537, 2008). "Low syndecan-1 expression was observed more frequently in CRC than adenomas and normal mucosae." (PMID 33437261, 2021). "Notably, in the colon of Sdc1-KO mice larger pedunculated adenomas with villous architecture were abundantly present, while smaller, sessile adenomas were mostly found in the colon of wt mice." (PMID 28350804, 2017). "high membranous/cytoplasmic staining of syndecan-1 was observed in 130 (57.4%), 36 (87.8%), and 34 (91.9%) cases of CRC, adenomas, and normal mucosae, respectively." (PMID 33437261, 2021). "There is a statistically significant difference in syndecan-1 expression between CRC and adenomas (p=0.0058) and normal mucosae (p=0.0017)." (PMID 33437261, 2021).
chronic heart failure (3 papers, 2019 to 2023). "Several studies have investigated syndecan-1 and -4 as potential circulating biomarkers in heart disease, with a focus on ischemia and MI, dilated cardiomyopathy (DCM), and acute and chronic heart failure." (PMID 37189684, 2023).
colon adenocarcinoma (3 papers, 2008 to 2025). "Previous studies have already proved that syndecan-1 expression is down regulated in case of colon adenocarcinomas compared to normal colon epithelium, and this has a strong association with the size of the tumorous tissue." (PMID 30826971, 2020). "Compared to normal colon epithelium the amount of syndecan-1 proved to be significantly reduced in primary colon adenocarcinomas." (PMID 30826971, 2020). "Syndecan-1 immunoreactivity is decreased in the majority of human colon adenocarcinomas in correlation with TNM stage and local lymph node metastasis." (PMID 18590537, 2008). "Syndecan-1 immunoreactivity was decreased in the majority of human colon adenocarcinomas in correlation with TNM stage and metastasis to local lymph nodes." (PMID 18590537, 2008). "Here we have examined syndecan-1 expression and its potential prognostic value with reference to a clinically annotated tissue microarray for human colon adenocarcinomas." (PMID 18590537, 2008). "SNV analysis revealed a high mutation rate of SDC1 in pan-cancer, Skin Cutaneous Melanoma (SKCM), Ovarian serous cystadenocarcinoma (OV), Colon adenocarcinoma (COAD) and UCEC." (PMID 41364407, 2025).
enteropathy (3 papers, 2013 to 2017). "The abnormities of Sdc1 and HPSE under HG conditions might provide an alternative perspective to better interpret HG induced/related enteropathy." (PMID 25702768, 2015).
epithelioid mesothelioma (3 papers, 2013 to 2021). "In epithelioid mesothelioma cells, syndecan-2 is mainly found in the cytoplasm, while syndecan-1 is mainly located at the cell membrane, from where it may be shed into extracellular fluids." (PMID 23991032, 2013).
germ cell tumor (3 papers, 2019 to 2025). A benign or malignant, gonadal or extragonadal neoplasm that originates from germ cells. "In contrast, SDC1 expression was negatively correlated with the scores for DNA, EREG-methss, DMPss, ENHss, RNAss and EREG in Testicular Germ Cell Tumors (TGCT), LUAD." (PMID 41364407, 2025).
hepatitis C (3 papers, 2019 to 2020). "On the other hand, if we took the etiology into consideration, hepatitis C positivity went together with significant elevation of syndecan-1." (PMID 30826971, 2020). "At early stages of hepatitis C virus infection, SDC1 and virions colocalize at the plasma membrane and are internalized in endosomes of hepatocyte, and knocking down SDC1 inhibits HCV infection." (PMID 32575635, 2020).
invasive carcinoma (3 papers, 2007 to 2021). A carcinoma that is not confined to the epithelium, and has spread to the surrounding stroma. "Second, the expression of syndecan-1 in the stroma is characterised by the appearance of a strong immunoreactivity for syndecan-1 in the reactive stroma of invasive carcinomas." (PMID 18542065, 2008). "Expression of c-met (P < 0.001) and Sdc1 (P = 0.037) was significantly more frequent in the subgroup of pure DCIS than in the subgroup of DCIS with a coexistent invasive carcinoma." (PMID 17244359, 2007). "The markers c-met and Sdc1 were significantly more frequently expressed in pure DCIS than in DCIS with a coexistent invasive carcinoma." (PMID 17244359, 2007). "Regarding the association between the expression pattern of Sdc1, E-cad and c-met with disease progression, future studies could investigate the correlation with expression for coexisting DCIS and invasive carcinoma." (PMID 17244359, 2007). "When co-cultured with highly invasive carcinoma cells, those MEFs that were SDC1+/+ enhanced the growth of carcinoma cells by 40% compared with SDC1−/− MEFs." (PMID 33669066, 2021). "Expression of c-met and syndecan-1 was significantly more frequent in the subgroup of patients with pure DCIS than in those with DCIS and a coexisting invasive carcinoma." (PMID 17244359, 2007).
ischemic stroke (3 papers, 2024 to 2026). A stroke disorder caused by obstruction of blood flow to the brain, due to thrombotic (local blood clot formation) or embolic (due to a blood clot or other material traveling from another site) event. "The shedding of hyaluronan and syndecan-1 following ischemic stroke in a rodent t-MCAO model was correlated with increased caveolae-mediated endocytosis across the BBB." (PMID 39125975, 2024). "Syndecan-1 levels are being used to predict the response to tissue plasminogen activator (tPA) and mechanical thrombectomy in the treatment of ischemic stroke." (PMID 39125975, 2024). "In addition, we demonstrate that platelet activation induces the mechanosensors Piezo1 and syndecan-1, sensitizing brain endothelial cells to shear-stress alterations characteristic of ischemic stroke." (PMID 42121873, 2026).
leptospirosis (3 papers, 2021 to 2023). A contagious bacterial infection caused by spirochetes of the genus Leptospira. "Few studies attempt to investigate the value of biomarkers such as syndecan-1, intercellular adhesion molecule-1, neutrophil gelatinase-associated lipocalin, and defensinα1 in leptospirosis-associated AKI." (PMID 34124239, 2021).
liver dysfunction (3 papers, 2017 to 2025). "If syndecan-1 were cleared primarily in the liver or kidney, then the association between elevated levels and kidney and liver dysfunction might simply reflect impaired clearance." (PMID 28986821, 2017). "This is consistent with the current study observation of increased SDC1 levels in individuals with MetS, especially those with elevated ALT, and suggests a potential link between SDC1, liver dysfunction and metabolic disorders." (PMID 41039734, 2025).
mesenchymal tumors (3 papers, 2012 to 2013). "Given this low syndecan-1 level in mesenchymal tumors, the expression, and function of syndecan-1 is far less studied than in carcinomas." (PMID 24392351, 2013). "Syndecan-1 seems to control the expression of other HSPGs in mesenchymal tumors, although the effect varies in different cell-types and also in the same tumor with various differentiation." (PMID 24392351, 2013). "Increased expression of syndecan-1 in mesenchymal tumors changes the tumor cell morphology to an epithelioid direction whereas downregulation results in a change in shape from polygonal to spindle-like morphology." (PMID 24392351, 2013). "One interesting concept concerns possible growth inhibition by using soluble HS oligosaccharides or overexpression of syndecan-1 in mesenchymal tumors to hamper crucial biological responses including proliferation and migration." (PMID 24392351, 2013). "Experimentally induced overexpression of syndecan-1 in mesenchymal tumors changes the tumor cell morphology in an epithelioid direction, whereas downregulation results in a change in shape of cells from polygonal to spindle-like." (PMID 24392351, 2013). "In mesenchymal tumors its expression level is generally low, hence only few studies have addressed syndecan-1’s role and regulation in these tumors." (PMID 23144729, 2012). "A number of mesenchymal tumours, especially the ones that show epitheloid morphology, express syndecan-1." (PMID 22745764, 2012). "The objective of this study is to reveal genes and pathways influenced by syndecan-1 in malignant pleural mesothelioma for a better understanding of its importance for the malignant behavior of this mesenchymal tumor." (PMID 23144729, 2012).
mucositis (3 papers, 2018 to 2021). Mucositis is inflammation and damage of the mucous membranes lining the mouth and other parts of the gastrointestinal (GI) tract. "Although the mucositis-mitigating effects of DS could partially be based on reduced inflammation and reduced local hypoxia, the main mechanism appears to be the reinforcement of epithelial cell cohesion based on the upregulation of tight as well as adherens junctions, likely via syndecan-1 (Sdc 1)." (PMID 29882770, 2018).
myocardial ischemia (3 papers, 2019 to 2024). A disorder of cardiac function caused by insufficient blood flow to the muscle tissue of the heart. "The exact physiological and pathophysiological role of sdc1 in cardiac ischemia and ischemic heart failure are beyond the scope of this paper." (PMID 31797997, 2019).
Nephropathy (3 papers, 2020 to 2021). A nonspecific term referring to disease or damage of the kidneys. "Co-localization of properdin with syndecan-1 on PTECs in an adriamycin induced nephropathy model suggested a role for the heparan sulfated proteoglycan (HSPG) syndecan-1 in the tubular binding of properdin." (PMID 32849563, 2020). "Insulin promotes shedding of SDC1 ectodomains and increased inflammatory mediators and proinflammatory monocytes in patients with type-1 diabetes and nephropathy have been correlated with increased plasma SDC1 levels." (PMID 32508807, 2020). "A study, comparing the inflammation status in DM with/without nephropathy, demonstrated that plasma levels of proinflammatory monocytes as well as circulatory inflammatory mediators, such as PAI-1, syndecan-1, VEGF, IL-1β, IL-1Ra, and CCL4, increased in nephropathy subjects." (PMID 34941711, 2021).
neuroblastoma (3 papers, 2009 to 2016). Neuroblastoma (NB) is the most common solid, extracranial childhood tumor. "We therefore chose to first examine the roles of PRPS2 and SDC1 that have been associated with rapid tumor progression and metastasis in certain types of human cancers other than neuroblastoma." (PMID 27448979, 2016). "Finally, we analyzed PRPS2 and SDC1 expression and their association with clinical outcome in the 649 neuroblastoma expression array dataset." (PMID 27448979, 2016). "Our findings that high levels of expression of PRPS2, SDC1 and also SLC7A6 are associated with poor clinical outcome in neuroblastoma, and that PRPS2 and SDC1 are important in proliferation, suggest that these genes may facilitate tumor progression in MYC- and MYCN-driven cancers." (PMID 27448979, 2016). "In particular, we have identified PRPS2 and SDC1 as genes that are positively regulated by both MYCN and TFAP4, and which represent novel candidate therapeutic targets for MYCN-driven neuroblastoma." (PMID 27448979, 2016). "Taken together, these data indicate that both PRPS2 and SDC1 are co-operatively regulated by both MYCN and TFAP4 in neuroblastoma cells." (PMID 27448979, 2016). "Microarray analysis identified genes regulated by both MYCN and TFAP4 in neuroblastoma cells, including Phosphoribosyl-pyrophosphate synthetase-2 (PRPS2) and Syndecan-1 (SDC1), which are involved in cancer cell proliferation and metastasis." (PMID 27448979, 2016). "Kaplan–Meier survival analysis showed that high levels of either PRPS2 or SDC1 expression were strongly associated with poor EFS and OS, suggesting that both these genes may play important roles in MYCN-driven neuroblastoma cell proliferation and tumor progression." (PMID 27448979, 2016).
parasitemia (3 papers, 2008 to 2021). "As with P. knowlesi, in patients with vivax malaria syndecan-1 was inversely correlated with platelet count on enrolment, remaining significant after controlling for parasitemia (r = − 0.50, p = 0.001)." (PMID 33963210, 2021). "After adjusting for parasitemia, plasma syndecan-1 also correlated with ADMA (r = 0.45, p < 0.001), angiopoietin-2 (r = 0.44, p = 0.002), and ICAM-1 (r = 0.53, p < 0.0001)." (PMID 33963210, 2021).
primary effusion lymphoma (3 papers, 2013 to 2021). A large B-cell lymphoma located in the body cavities, characterized by pleural, peritoneal, and pericardial fluid lymphomatous effusions and that is always associated with human herpes virus-8 (HHV-8). "Nutlin-3-PLGA NPs have also been formulated, via nanoprecipitation, and conjugated to the human monoclonal antibody against CD-138/Syndecan-1 (anti-Syndecan-1) to target primary effusion lymphoma." (PMID 34683830, 2021).
sarcoma (3 papers, 2013 to 2022). A usually aggressive malignant neoplasm of the soft tissue or bone. "Syndecan-1 is the main syndecan of epithelial malignancies, whereas in sarcomas its expression level is generally low, in accordance with their mesenchymal phenotype and highly malignant behavior." (PMID 24392351, 2013).
scleroderma (3 papers, 2018 to 2023). Scleroderma is a rare autoimmune connective tissue disorder characterized by abnormal hardening of the skin and, sometimes, other organs. "We found signalling from ADSCs via FGF2 to SDC1 on FB5 in both datasets and FB2 in scleroderma." (PMID 37443817, 2023).
skin cancer (3 papers, 2022 to 2025). "However, in a separate study, it was determined that syndecan-1 expression was decreased in BCC, cSCC, and metastatic human skin cancers compared to normal human skin." (PMID 35572966, 2022).
small cell lung carcinoma (3 papers, 2013 to 2021). Small cell lung cancer (SCLC) is a highly aggressive malignant neoplasm, accounting for 10-15% of lung cancer cases, characterized byrapid growth, and early metastasis. "Additionally, pre-treatment serum SDC1 levels can predict outcome in small cell lung cancer patients treated with platinum-based chemotherapy." (PMID 34503301, 2021).
synovitis (3 papers, 2009 to 2024). Inflammation of a synovial membrane. "In trying to explain the more pronounced expression of SDC1 in lower-grade synovitis than in higher-grade synovitis, we should consider that, similar to cytokines, syndecans could serve as both pro-inflammatory and anti-inflammatory molecules." (PMID 38674142, 2024). "Still, we concluded that syndecans (SDC1, SDC4), exostosins (EXT2) and sulfotransferases (NDST1) play a role in the progression and control of synovitis and, consequently, are potential therapeutic targets." (PMID 38674142, 2024). "SDC1, SDC4, NDST1 and EXT2 seem to be involved as inflammation moderators in low-grade OA synovitis and, therefore, should be further investigated as potential markers of disease progression and therapeutic goals." (PMID 38674142, 2024). "According to our study, the immunoexpression of SDC1, NDST1 and EXT2 is significantly increased in the intimal cells of OA synovial membrane in patients with lower histological synovitis scores and SDC4 in patients with higher synovitis scores, in comparison with non-OA controls." (PMID 38674142, 2024).
type 1 diabetes (3 papers, 2009 to 2020). "We have previously shown that level of the proteoglycan syndecan-1 in blood is associated with ultrastructural kidney changes in young persons with type 1 diabetes." (PMID 19758433, 2009). "We have recently shown that serum concentrations of the proteoglycan syndecan-1 is higher in subjects with type 1 diabetes and microalbuminuria than in those without microalbuminuria suggesting that it is a potential serum marker for kidney changes." (PMID 19758433, 2009).
ulcerative colitis (3 papers, 2017 to 2024). An inflammatory bowel disease involving the mucosal surface of the large intestine and rectum. "We found that the patients suffered ulcerative colitis had high serum SDC1 levels,presented with increased levels of P65, tumour necrosis factor alpha (TNF‐α) and IL‐1β and higher circulating neutrophils." (PMID 27558380, 2017).
acne (2 papers, 2024). An inflammatory process of the sebaceous glands which is characterized by comedones, nodules, papules and/or pustules on the skin. "Moreover, the function of the other genes, including FAS, SDC1, ANGPTL2, IL-15RA, INHBA, and OSMR in lymphocytes, keratinocytes, fibroblasts, and smooth muscle, are yet to be explored, suggesting that acne involves not only the skin’s surface but also a wider systemic dysregulation." (PMID 38854033, 2024).
acute leukemia (2 papers, 2020 to 2025). A clonal (malignant) hematopoietic disorder with an acute onset, affecting the bone marrow and the peripheral blood. "ALL patients also had a high syndecan-1 level compared to the control group (p = 0.012), which indicates that syndecan-1 has the potential to be a useful biomarker for acute leukemia." (PMID 32983743, 2020). "We conducted this study to investigate the prognostic role of syndecan-1 in acute leukemia." (PMID 32983743, 2020). "Interestingly, doxorubicin, which is also used in the treatment of acute leukemia, is one of the chemotherapeutic agents that enhance the shedding of syndecan-1." (PMID 32983743, 2020). "In summary, emerging CAR-T cell therapeutic approaches may become the forefront of the exploitation of proteoglycan antigens, as firmly suggested by the promising preclinical efforts with CAR-T-based approaches targeting CSPG4 and Syndecan-1/CD138 in childhood and adult acute leukemia." (PMID 39980017, 2025). "Therefore, syndecan-1 has limitations in differentiating between both types of acute leukemia." (PMID 32983743, 2020).
adenomyosis (2 papers, 2024). The growth of endometrial tissue inside the muscular wall of the uterine corpus. "The main outcome measures were the morphology of the endometrium, syndecan-1 (CD138) immunohistochemical staining, clinical characteristics, and prevalence of CE in the adenomyosis subgroups." (PMID 39014375, 2024).
anthrax (2 papers, 2006 to 2023). "Syndecan-1 protein is found to be the major component of thrombi and plays a role of thrombus formation in a mouse model of anthrax." (PMID 36675479, 2023).
aortic aneurysm (2 papers, 2022 to 2025). A ruptured aneurysm located in the wall of the proximal portion of the descending aorta proceeding from the arch of the aorta. "After a week of treatment, and especially during the process of aortic aneurysm formation, an increased synthesis of SDC-1 emerged, associated with the infiltration of macrophages, mainly at the level of the periadventitial aorta." (PMID 39940978, 2025). "The role of SDC-1 on TAA development was investigated in an animal model using BAPN and Ang II, known to induce aortic aneurysms in C57Bl/6J mice." (PMID 35548440, 2022).
blood pressure (2 papers, 2022 to 2023). "We also noted that low blood pressure (systolic BP < 90 mmHg) was relevantly associated with increased levels of syndecan-1, while an impaired systolic function (LVEF < 40%) did not considerably influence the concentration of biomarker." (PMID 37109427, 2023).